B2M (beta-2-microglobulin)
Diseases named in the same sentence as B2M in open-access papers (continued):
Sharing a sentence is not in itself a finding about the gene and the disease.
metastatic tumor (6 papers, 2019 to 2024). "The mutation profile of metastatic lesions resembles that of primary lesions in each patient, but a new/second mutation in beta-2 microglobulin (B2M) gene was identified in the metastatic tumor of respective patients, suggesting that B2M mutations may contribute to secondary resistance to ICIs." (PMID 33561950, 2021). "Overall, we stained B2M and HLA-A on a large set of primary (n= 420) and metastatic tumor samples (n=213 baseline and 116 matched on-treatment samples) of various histologies." (PMID 38455061, 2024). "We have then used these assays to analyze the expression of B2M and HLA-A in diverse, primary, and metastatic tumors including longitudinal samples acquired before start and during treatment with various immunotherapy drug candidates." (PMID 38455061, 2024). "CDC6, DHFR, E2F1, H2AFZ, MCM2, GUSB and B2M were significantly higher in patients with metastatic disease than in healthy controls, and CDC6, DHFR and E2F1 were significantly higher in metastatic patients than in localized patients." (PMID 37046768, 2023). "There is a significant reduction in the expression of the antigen presenting genes B2M, HLA-A, HLA-B, and HLA-C in the recurrent/metastatic tumors relative to the primary tumors." (PMID 33796222, 2021). "CHMP1A, B2M, and RSU1 loss alterations were significantly enriched in RB1-loss primary tumors at a frequency of 7%–18% above RB1-WT primary tumors and were significantly enriched in RB1-loss metastatic tumors at a frequency of 16%–23% above RB1-loss primary tumors." (PMID 38751776, 2024). "In contrast to B2M, there was no obvious trend for an altered frequency of HLA-A expression in metastatic diseases versus primary tumors (meta regression analysis Odds Ratio 1.16, CI 0.61-2.2, p-value ~ 0.65)." (PMID 38455061, 2024). "The patient with two metastatic tumor biopsies expressed low to no MHC-I, were negative for B2M, PD-L1, NY-ESO-1, and MAGE-A, and were positive for B7-H3 and B7-H4." (PMID 31692889, 2019).
systemic amyloidosis (6 papers, 2012 to 2025). "The first genetic variant of β2‐microglobulin (b2M) associated with a familial form of systemic amyloidosis has been recently described." (PMID 26990223, 2016). "D76N b2M is the first described genetic variant of b2M associated with a familial form of systemic amyloidosis." (PMID 26990223, 2016). "There are a great variety of mechanisms of B2M alterations, and the causative mutations are not only found in various types of tumors but also in systemic amyloidosis, in which misfolded proteins caused by the B2M gene mutations exhibit a strongly enhanced propensity for amyloid aggregation." (PMID 36046045, 2022). "The aggregation prone D76N beta-2 microglobulin mutant causes systemic amyloidosis." (PMID 29695721, 2018). "B2M is responsible for systemic amyloidosis, which can dysregulate the levels of BDNF and NGF." (PMID 32059688, 2020).
Thrombocytopenia (6 papers, 2016 to 2024). A reduction in the number of circulating thrombocytes. "Fetal thrombocytopenia and fetal serum levels of beta-2 microglobulin acquired through fetal blood sampling have been suggested to precede the development of brain lesions." (PMID 38610901, 2024). "Laboratory markers of the severity of infection including thrombocytopenia and high serum levels of beta-2-microglobulin in fetal blood have been suggested to precede the development of brain lesions." (PMID 26808779, 2016). "Similarly, a higher proportion of patients in these groups had thrombocytopenia (platelets < 150 × 109/L) (P < 0.001), beta2microglobulin (B2M) levels >5.5 μg/ml (P = 0.03), and ISS stage III disease (P = 0.04)." (PMID 32782240, 2020).
lupus nephritis (5 papers, 2021 to 2025). Glomerulonephritis in the context of systemic lupus erythematosus. "A strong correlation between lupus nephritis (LN), disease activity, and serum beta 2-microglobulin (b2MG) was observed." (PMID 36205758, 2023). "A similar pattern was also observed for DDX5, B2M, and TMSB4X in CKD/lupus nephritis, and for GATM in the control group." (PMID 39974940, 2025).
lymph node metastasis (5 papers, 2008 to 2024). "B2M mutations were strongly associated with exclusively peritoneal/peritoneal and lymph node metastases (p=0.0055)." (PMID 34168989, 2021). "In a separate study conducted with a small set of tissues (n=14), we observed that B2M maintained its high prognostic accuracy for lymph node metastases (AUC=0.79) when more classical reference control genes TBP or UBP were substituted for Spint2 (not shown)." (PMID 18506145, 2008).
Obesity (5 papers, 2021 to 2026). Accumulation of substantial excess body fat. "Collectively, these findings suggest that the aberrant increase in B2M in human adipose tissue is linked to adipose tissue inflammation and iron excess, both of which are implicated in human obesity-related metabolic disorders." (PMID 41330906, 2025). "Collectively, these findings demonstrate that interfering with B2M expression in EpiWAT during obesity progression effectively alleviates obesity and associated metabolic disorders." (PMID 41330906, 2025). "According to the previously established study, an elevated level of serum B2m is associated with various adverse health effects, including overweight/obesity." (PMID 38931172, 2024). "Furthermore, GSEA revealed that in patients with obesity, the antigen processing and presentation, iron uptake and transport, and ferroptosis pathways associated with B2m were significantly upregulated." (PMID 41330906, 2025). "Taken together, these data suggest that hypertrophic adipocytes act as APCs to potently activate adipose-resident CD8+ T cells in a B2M- and cell contact-dependent manner during obesity." (PMID 41330906, 2025). "Our study demonstrated the pivotal role of adipocytes in driving chronic inflammation and metabolic disorders in obesity via two B2M-dependent yet mechanistically distinct pathways." (PMID 41330906, 2025). "Collectively, these results strongly indicate a pivotal role of B2M in adipocytes in driving obesity and related inflammation and metabolic disorders." (PMID 41330906, 2025). "Next, to investigate the regulatory effect of B2M on adipocytes during obesity and its potential mechanisms, we conducted a comparative analysis of the RNA-seq data obtained from mature adipocytes in the EpiWAT of control and B2mcKO mice fed a HFD." (PMID 41330906, 2025). "To elucidate the role of B2M in iron homeostasis within adipocytes during obesity, we first assessed the iron load in adipocytes of B2mf/f and B2mcKO mice under NCD or HFD conditions." (PMID 41330906, 2025). "To determine the relevance of B2M in human obesity, we analyzed RNA-seq data (GEO: GSE152991) of SAT from both obese individuals and healthy lean controls." (PMID 41330906, 2025). "To assess the role of B2M in adipocytes in HFD-induced obesity, we generated adipocyte-specific B2M knockout (B2mcKO) mice." (PMID 41330906, 2025). "More importantly, our analysis of transcriptome data from human SAT and VAT, combined with B2M detection in human adipocyte samples, consistently confirms the significant role and clinical translational value of B2M in obesity-related chronic inflammation and metabolic dysfunction in humans." (PMID 41330906, 2025). "Furthermore, AAV9-mediated targeted reduction in B2M in adipose tissue effectively ameliorated HFD-induced obesity, adipose inflammation and metabolic abnormalities in mice." (PMID 41330906, 2025). "Additionally, our findings highlight the translational potential of targeting adipocyte B2M inhibition as a therapeutic strategy for obesity-related chronic inflammation and metabolic disorders." (PMID 41330906, 2025). "Collectively, these findings imply that B2M might play a significant role in the response of adipocytes to HFD-induced obesity." (PMID 41330906, 2025). "To further investigate the therapeutic potential of specific interventions for B2M expression in adipose tissue during obesity, we employed an adipose-targeted adeno-associated virus type 9 (AAV9) vector carrying B2m-shRNA (AAV9-B2m) or ZsGreen (AAV9-null control)." (PMID 41330906, 2025). "Another research study demonstrated that β2-microglobulin (B2M) knockout mice showed a deficiency of NKT cells and were insensitive to insulin resistance induced by obesity, indicating that NKT cells might participate in the progression of insulin resistance induced by obesity." (PMID 33413697, 2021).
Obesity (continued). "Given the critical role of CD8+ T cells in adipose tissue inflammation and their reliance on MHC-I/B2M for activation, we hypothesized that hypertrophic adipocytes might participate in CD8+ T-cell activation through the MHC-I antigen presentation pathway during obesity." (PMID 41330906, 2025).
peripheral arterial disease (5 papers, 2012 to 2021). A disorder of the arteries supplying the upper and lower extremity and the visceral organs. "β2-microglobulin (B2M) is reported to associate with peripheral arterial disease and adverse cardiovascular outcomes." (PMID 28249620, 2017). "In addition, B2M is a predictor of peripheral artery disease, and increased B2M levels are significantly associated with adverse CV outcome in patients with prevalent asymptomatic carotid atherosclerosis." (PMID 24683472, 2014). "Finally, in peripheral arterial disease patients, circulating B2M is elevated and correlates with the severity of disease independent of other risk factors." (PMID 33467687, 2021). "Serum beta 2-microglobulin (B2M) levels have been found to be increased in patients with peripheral arterial disease (PAD), yet it is still unknown whether B2M correlates with PAD intensity." (PMID 24757603, 2012). "Recent studies have shown that circulating B2M is elevated in accordance with the acuteness of disease in peripheral arterial disease (PAD) patients." (PMID 28249620, 2017).
renal tubular dysfunction (5 papers, 2011 to 2021). "An increase in urine beta-2-microglobulin, considered a sensitive and specific indicator of renal tubular dysfunction associated with TDF, was the only renal AE that was reported in more than one participant." (PMID 34930140, 2021). "Increased urinary excretion of sodium, calcium, phosphorus, magnesium, uric acid, N-acetyl glucosamine, beta 2-microglobulin, retinol binding protein, and glucose in association with decreased urinary osmolality are symptoms of renal tubular dysfunction in thalassemic patients." (PMID 34872508, 2021). "Biomarkers of renal tubular dysfunction such as urinary beta-2-microglobulin or N-acetyl-beta-D-glucosaminidase and of glomerular kidney dysfunction (urinary albumin) were found to be associated with Cd exposure." (PMID 21726464, 2011).
Splenomegaly (5 papers, 2021 to 2025). Abnormal increased size of the spleen. "Our patient exhibited several high-risk features: chronic hypocomplementemia, elevated beta-2-microglobulin, progressive pancytopenia, splenomegaly, and anti-SSA positivity." (PMID 41531558, 2025). "In this patient, the combination of splenomegaly, neutropenia, and elevated beta-2-microglobulin, along with other findings such as a positive serology for schistosomiasis, required the exclusion of several differential diagnoses." (PMID 39834986, 2024). "Even in Case 2 the important splenomegaly and increased beta-2 microglobulin levels could have suggested a lymphoproliferative disorder." (PMID 33672504, 2021). "Clinically, 8% of patients (28/346) presented with splenomegaly, 47.4% had B symptoms, 28.9% had increased LDH, and 34.1% had elevated serologic B2M." (PMID 36606194, 2022). "Beta- 2 microglobulin and ferritin levels were increased, whilst further tests performed for hemolytic anemia and splenomegaly were all negative." (PMID 33672504, 2021).
tuberculosis (5 papers, 2011 to 2025). A chronic, recurrent infection caused by the bacterium Mycobacterium tuberculosis. "Mutations in additional ECM increased genes such as Tap1 and B2m also cause susceptibility to tuberculosis, while their direct effects on ECM susceptibility have yet to be tested." (PMID 23853600, 2013). "B2M showed moderately stable expression; however, its transcription is known to increase during immune activation and tuberculosis, warranting caution when using this gene." (PMID 41303702, 2025). "Our study is unique and the first to report changes in acute phase reactants (albumin, CRP, and beta-2-microglobulin) as measures of inflammation and how their levels relate to repletion of body composition components during treatment of tuberculosis." (PMID 22567264, 2011). "Thus the aim of this study was to determine the levels of CRP, Neopterin and B2M in relation to pulmonary tuberculosis disease severity at recruitment and changes in response to TB treatment in a cohort of TB patients from The Gambia." (PMID 26951717, 2016).
type 2 diabetes (5 papers, 2018 to 2023). "Serum B2M concentration was positively correlated with the general population and patients with the chronic obstructive pulmonary disease, type 2 diabetes, and acute coronary syndrome." (PMID 35647083, 2022). "Serum KIM-1 and B2M independently improve prediction of renal decline from an eGFR of 30–75 ml min−1 [1.73 m]−2 in type 2 diabetes beyond clinical factors and prior eGFR and are robust to varying sample storage conditions." (PMID 30288572, 2019). "We have shown that the combination of B2M and KIM-1, measured in serum, in addition to clinical covariates, significantly improves prediction of renal function decline in type 2 diabetes on top of clinical data." (PMID 30288572, 2019).
Cirrhosis (4 papers, 2012 to 2025). A chronic disorder of the liver in which liver tissue becomes scarred and is partially replaced by regenerative nodules and fibrotic tissue resulting in loss of liver function. "Serum B2M level may be used as a marker for HCV disease progression toward cirrhosis and carcinoma." (PMID 37575948, 2023). "Genes involved in cirrhosis development (ABCG2, CTNNB1, B2M, IFNAR1, IFNAR2), and hepatic cholestasis (CYP7B1) were found significantly down-regulated in patients without HCC." (PMID 22792259, 2012). "Increased levels of B2M may serve as a potential biomarker of the severity of ALD, as proposed for HCV cirrhosis and carcinoma." (PMID 36582223, 2022).
head and neck cancer (4 papers, 2017 to 2023). A primary or metastatic malignant neoplasm affecting the head and neck. "However, the minimum and maximum (min-max) range for head and neck cancer cell line SCC6 was calculated to be 0.490 for HPRT1 and 2.990 for ACTB while for SCC-1483 it was 0.409 for B2M and 4.093 for ACTB respectively." (PMID 28262749, 2017). "In our study, we found that there is a significant benefit between the main target B2M gene and its corresponding receptor gene in the hypopharyngeal carcinoma microenvironment, but this target and the corresponding targeting drugs have not been further studied or applied in head and neck cancer." (PMID 36460803, 2023). "Unlike head and neck cancer cell lines, TBP was stably expressed in A549 and NCI-H226 across all IR dose treatment groups while PP1A, GAPDH and B2M expression was exclusively expressed at 2, 4 and 6 Gy respectively." (PMID 28262749, 2017).
iron overload (4 papers, 2009 to 2025). "Indeed, B2M-deficient mice present iron overload and hemochromatosis, whose pathogenesis likely involves other B2M-interacting protein(s)." (PMID 32664348, 2020). "However, at least for M. tuberculosis infection, the defect of B2m−/− mice may be due to iron overload or hemochromatosis, as β2-microglobulin associates with the MHC I family member HFE, which is involved in iron homeostasis." (PMID 19730693, 2009). "In this study, B2M knockout destabilized HFE on the adipocyte membrane, disrupting the HFE/B2M-TFR2-hepcidin-FPN axis and preventing HFD-induced iron overload." (PMID 41330906, 2025). "In addition to lacking cell-mediated immune functions, B2m−/− mice have an additional phenotype of iron overload, similar to human hemochromatosis." (PMID 19730693, 2009).
ischemic stroke (4 papers, 2022 to 2024). A stroke disorder caused by obstruction of blood flow to the brain, due to thrombotic (local blood clot formation) or embolic (due to a blood clot or other material traveling from another site) event. "In women patients with stoke, there was a positive correlation between plasma B2M levels and risk of ischemic stroke." (PMID 38743119, 2024). "A study revealed that high levels of B2M were associated with an increased risk of ischemic stroke among women, which is consistent with our findings." (PMID 37155257, 2023). "The role of B2m protein in cerebral ischaemia is unclear; however, its serum levels are associated with an increased risk of ischaemic stroke in humans." (PMID 35451185, 2022). "In addition, Rist PM and his partners found that high levels of B2M were associated with an increased risk of ischemic stroke among women." (PMID 37786415, 2022). "LCN-2 and B2M correlate with oxidative stress, which plays an important role in the pathogenesis of ischaemic stroke." (PMID 37155257, 2023).
myocardial infarction (4 papers, 2011 to 2022). Gross necrosis of the myocardium, as a result of interruption of the blood supply to the area, as in coronary thrombosis. "B2m is widely used as a housekeeping gene, but its use has been shown to be inappropriate in myocardial infarction studies." (PMID 33514846, 2021). "We furthermore caution against the use of Gapdh, Polr2a, Actb, B2m and Eef1a1 for gene expression normalization in myocardial infarction studies because of selective up- or downregulation after myocardial infarction." (PMID 21858224, 2011). "Gapdh, Polr2a and Actb consistently showed the highest gene expression variability and the expression levels of Gapdh, Polr2a, Actb, B2m and Eef1a1 were found to be selectively up- or downregulated after myocardial infarction." (PMID 21858224, 2011). "We furthermore caution against the use of Gapdh, Polr2a, Actb, B2m and Eef1a1 for gene expression normalization in myocardial infarction studies because of selective up- or downregulation after myocardial infarction, which could potentially lead to biased study outcomes." (PMID 21858224, 2011). "For instance, in the rat model of myocardial infarction, beta-2 microglobulin (B2M) negative UC-MSC lost the ability to induce CD8+ T cell immune rejection response by the B2M-UCMSC exosomes/miR-24/Bcl-2-like protein 11 (Bim) pathway after B2M-UCMSC injection to the heart." (PMID 32117221, 2020).
osteosarcoma (4 papers, 2020 to 2025). A usually aggressive malignant bone-forming mesenchymal neoplasm, predominantly affecting adolescents and young adults. "The team led by Weijian Liu in China utilized scRNA-seq technology to characterize the immunosuppressive tumor microenvironment profile of osteosarcoma (OS) and discovered that MHC-I (HLA-A, HLA-B, and HLA-E)/B2M genes were downregulated, indicating diminished tumor immunogenicity in OS." (PMID 40191187, 2025). "To further examine whether the downregulation of MHC-I can be generalized across osteosarcoma, we evaluated the expression of MHC-I and B2M through immunohistochemistry (IHC) staining in sections from OS patients." (PMID 36596773, 2023). "Next, we compared thetranscriptional stability of several normalizers that were formerly recommendedfor use in canine osteosarcoma without transcriptome-wide expression profiling forthis context such as OAZ1 or B2M,HNRNPH, RPS5 and RPS19." (PMID 32296879, 2020).
Parkinson disease (4 papers, 2018 to 2024). A progressive degenerative disorder of the central nervous system characterized by loss of dopamine producing neurons in the substantia nigra and the presence of Lewy bodies in the substantia nigra and locus coeruleus. "The involvement of B2M in the progression of Parkinson's disease and other neurodegenerative disorders, as well as its potential utility as a diagnostic adjunct and prognostic indicator, remain unknown." (PMID 38743119, 2024).